INS (insulin)
Diseases named in the same sentence as INS in open-access papers (continued):
Sharing a sentence is not in itself a finding about the gene and the disease.
Hyperglycemia (continued). "We found that these animals developed insulin-resistant hyperglycemia and skeletal muscle breakdown after operation." (PMID 33526980, 2021). "Regular insulin has already been frequently described in clinical practice for patients experiencing hyperglycaemia because of PN, either by dedicated intravenous infusion or directly added to PN admixtures." (PMID 33801784, 2021). "Stimulating glucose uptake by tissues via insulin signaling represents a potential coping mechanism against this persistent hyperglycemia." (PMID 34707105, 2021). "An increase in blood glucose levels due to insulin deprivation (hyperglycemia) can regulate the expression of genes related to protein degradation and synthesis." (PMID 34571935, 2021). "Insulin therapy, often needed to combat hyperglycaemia in T2D individuals, has been proven safe in large randomised controlled cardiovascular outcome trials." (PMID 34615525, 2021). "On hospital day 5, he received intravenous insulin for worsening hyperglycemia, after which he became unconscious." (PMID 34020705, 2021). "Although this model does not present all the characteristics of T2D, it exhibits a stable hyperglycemia that can be controlled with a hypoglycemic agent, such as a sulfonylurea, due to the responsiveness to insulin secretagogues." (PMID 34685869, 2021). "In principle, multiple inhibition of the protein tyrosine phosphatase 1B (PTP1B) and glycoside hydrolase proteins (3W37 and 3AJ7) is a promising strategy to suppress hyperglycemia and improve insulin sensitisation simultaneously." (PMID 35492788, 2021). "It is known that MetS is characterized by the inability of insulin to adequately suppress hepatic gluconeogenesis, leading to hyperglycaemia, hyperinsulinemia and eventually to T2D." (PMID 33513940, 2021). "It is widely known that chronic hyperglycemia per se has deleterious effects on the sensitivity of insulin." (PMID 34869586, 2021). "This disorder presents with diabetic ketoacidosis (DKA) or marked hyperglycemia due to low insulin levels and is usually treated with insulin." (PMID 34696808, 2021). "The NIRTURE Trial, a large multicentre randomized controlled trial used early insulin treatment prior to the onset of hyperglycaemia, with the aim of promoting anabolism." (PMID 34368024, 2021). "Sarcopenic obesity can reduce insulin sensitivity leading to hyperglycemia, which induces increased insulin secretion by the pancreas and hyperinsulinemia." (PMID 33919368, 2021). "Mean glucose and time in hyperglycemia (sensor glucose >10 mmol l−1) both decreased during days 8–20 without any difference in time spent in hypoglycemia or total daily insulin dose." (PMID 34349267, 2021). "Accordingly, robust hyperglycemia-induced endothelial dysfunction and altered insulin signaling-induced PVAT dysfunction seem both responsible for severe vascular dysfunction occurring just after 2 weeks of administration of S961 in mice." (PMID 34207844, 2021). "With a reduction in beta cell mass and impaired insulin secretion by the remaining beta cells, hyperglycaemia worsens and completes the vicious cycle that ends in a complete cessation of insulin secretion." (PMID 34680532, 2021). "PNDM is characterized by persistent hyperglycemia within the first 12 months of life, generally requiring continuous insulin treatment." (PMID 34681954, 2021). "Due to its multiple favorable effects, including the increase in insulin sensitivity and the mitigation of hyperglycemia, metformin is currently used for pharmacologic modulation of the hyperglycemic–hypermetabolic state that develops in severe burns." (PMID 34575946, 2021). "After one week of treatment, the co-agonist improved insulin sensitivity, corrected hyperglycemia, and lowered body weight." (PMID 35054422, 2021). "Particular emphasis has been given on the ability of taurine to enhance insulin sensitivity by negatively affecting hyperglycemia through the activation of the PI3K/Akt signal transduction pathway." (PMID 36699147, 2021).
Hyperglycemia (continued). "Glucotoxicity refers to long-term chronic hyperglycemia leading to downregulated insulin gene expression and chronic irreversibly decreased insulin synthesis." (PMID 33952301, 2021). "We also aimed to evaluate the mechanism of hyperglycaemia by estimating insulin secretion and sensitivity during and postexacerbation." (PMID 33855211, 2021). "Our present study clearly showed that AOS is efficacious in preventing hyperglycemia, possibly by increasing insulin sensitivity and improving IR by regulating the INS-R/IRS/Glut4 insulin signal pathway." (PMID 34497509, 2021). "The probable explanation for hyperglycemia appearing more often in the NEC-PVG group was that more severe infectious diseases inhibited the release of insulin, cytokines, or endotoxins, reduced glucose utilization, and increased cortisol or catecholamines." (PMID 34195163, 2021). "Type 1 diabetes (T1DM) is an autoimmune disorder characterized by the destruction of insulin-producing pancreatic β-cell and resultant hyperglycemia." (PMID 34262457, 2021). "While in conditions of glucose hypometabolism, brain levels of O-GlcNAc-modified proteins are reduced, hyperglycemia increases GlcNAcylation of proteins related to the INS pathway, thus contributing to INS resistance." (PMID 33815298, 2021). "Diazoxide is a potassium channel activator and blocks insulin secretion by opening potassium channels of β cells, resulting in hyperglycemia." (PMID 34830886, 2021). "Low circulating osteocalcin was lower in COVID-19 patients, in those with stress hyperglycemia, and in those in need for insulin infusion therapy." (PMID 34578888, 2021). "In rodent models of type 1 diabetes, glycogen stores are depleted, thereby contributing to the development of hyperglycemia, and hepatic glycogen is restored to normal levels after insulin treatment." (PMID 33667544, 2021). "Insulin resistance forces the pancreatic β-cells to produce more insulin to be able to prevent hyperglycaemia." (PMID 33498674, 2021). "On the other hand, thymol was also able to treat hyperglycemia by normalizing blood sugar, plasma insulin, HbA1c, and insulin resistance index." (PMID 34221086, 2021). "We found that active smoking induced hyperglycemia and significant reductions in serum insulin and leptin levels." (PMID 34917518, 2021). "These cytokines, together with cortisol, catecholamines, FFAs, and hyperglycemia accentuate and maintain the insulin resistance." (PMID 34068151, 2021). "We observed that exposure of rat pups to brief IH, in which ambient oxygen levels alternate between 10% and 21%, results in decreased blood insulin levels accompanied by hyperglycemia and abnormal glucose tolerance 3 weeks post-challenge." (PMID 34943374, 2021). "Hyperglycemia is common among corticosteroid-treated patients, but is easily controlled with rapid-acting insulin." (PMID 34955733, 2021). "In this context, fetal growth will dependent both on the degree of maternal hyperglycemia, and on the ability of the fetus to increase insulin secretion in response to hyperglycemia, i.e., its GCK genotype." (PMID 35069449, 2021). "TZDs are most known for their insulin-sensitizing ability and their leading role in the treatment of hyperglycemia, though are currently second- or third-line antidiabetic agents due to their adverse effects." (PMID 34298687, 2021). "Habits 5 and 6 are linked, as the purpose of data review is to identify patterns of hypoglycemia or hyperglycemia that would signal the need for changes in behavior and/or insulin management." (PMID 34709387, 2021). "From week 4–16, HFD mice exhibited progressively exaggerated insulin secretion in tandem with evident hyperglycemia." (PMID 33817571, 2021). "It is characterized by hyperglycemia through a defect in the β-cells function and/or decreased insulin sensitivity." (PMID 33668280, 2021).
Hyperglycemia (continued). "Its multifactorial etiology leads to persistent hyperglycemia, impaired carbohydrate and fat metabolism, chronic inflammation, and defects in insulin secretion or insulin action, or both." (PMID 34069422, 2021). "T1DM is a metabolic disease characterized by impaired insulin secretion and resultant hyperglycemia." (PMID 34262457, 2021). "Due to the central role of PI3Kα in regulating glucose metabolism, particularly insulin signalling, previously used PI3K inhibitors such as idelisib and copanlisib have already been associated with hyperglycemia." (PMID 34281618, 2021). "In our study, hyperglycemia was reduced to a normal level, and body weights were elevated by insulin therapy." (PMID 33446235, 2021). "Insulin promotes the transport of glucose into the cell and its lack translates into elevated BG (hyperglycemia)." (PMID 34064325, 2021). "Guidelines recommend that hyperglycaemia (readings >140) first be treated conservatively with the addition of the use of insulin to control of blood glucose when levels reach 180 mg/dl in the inpatient environment for all patients." (PMID 34505406, 2021). "We found that two anti-oxidant proteins (SOD2 and CAT) were decreased in 16-week-old diabetic mice, along with severe hyperglycemia and low insulin levels." (PMID 34249264, 2021). "First, chronic hyperglycemia leads to a decrease of insulin biosynthesis and/or secretion in the diabetic state, which is accompanied by decreased expression of insulin transcription factors." (PMID 34360682, 2021). "As a result, treatments involving pharmaceuticals primarily focus on controlling hyperglycemia by increasing insulin sensitivity, insulin secretion, and through the inhibition of carbohydrate digestive enzymes." (PMID 34885816, 2021). "Increased serum insulin levels and suppressing inflammatory mRNA expression were also observed in treated animals with the extract which were due to hyperglycemia." (PMID 34567150, 2021). "Type 1 diabetes (T1D) is a proinflammatory pathology that leads to the specific destruction of insulin producing β-cells and hyperglycaemia." (PMID 34421908, 2021). "Alpha cells secrete more glucagon during periods of low blood glucose (hypoglycemia), while beta cells secrete higher levels of insulin during periods of elevated blood glucose (hyperglycemia)." (PMID 34387389, 2021). "Children at this age are not mature enough to voice their symptoms of hypoglycemia in the situation of miscalculated insulin doses or symptoms of hyperglycemia." (PMID 34873537, 2021). "In type 1 diabetes, β-cell death due to autoimmune destruction occurs at the early stages of the disease and leads to a rapid reduction in insulin levels and reciprocal hyperglycemia." (PMID 33746901, 2021). "Diabetes is metabolic disorder that is characterized by chronic hyperglycaemia resulting from disturbances in insulin secretion and tissue resistance to its action." (PMID 33573121, 2021). "C646, a P300 acetyltransferase-specific inhibitor, significantly improved hyperglycemia and improved insulin sensitivity in obese mice." (PMID 33672754, 2021). "In fact, the accumulation of hepatic triglycerides in hepatocytes serves as a compensation mechanism to reduce persistent hyperglycemia, due to systemic insulin resistance." (PMID 34764881, 2021). "Mechanisms linking diabetes and cancer have invoked the mitogenic and anti-apoptotic actions of insulin and insulin-like growth factor 1, increased cytokine secretion, steroid hormone dysregulation, chronic inflammation, and hyperglycemia." (PMID 34426491, 2021). "In a study on diabetic rats, GPR40 activation showed improvements in hyperglycaemia and insulin response." (PMID 34827690, 2021). "Biomarkers related to energy metabolism and insulin signaling were examined to identify the effect of AME on hyperglycemia induced hepatic damage." (PMID 34679681, 2021).
Hyperglycemia (continued). "During hyperglycemia, induced with a clamp, insulin secretion increased when the hormones were co-infused, compared to the infusion of individual molecules." (PMID 35054422, 2021). "She rapidly developed worsening hyperglycemia with glucose levels above 400 mg/dL in the setting of methylprednisolone treatment and was started on an insulin infusion." (PMID 33992101, 2021). "These animals also presented fasting basal hyperglycemia, glucose intolerance, and impaired insulin sensitivity when compared to the control group." (PMID 33580916, 2021). "As hyperglycaemia was shown in particular to negatively affect regeneration following TSCI and TBI in humans and in vivo, clinical trials were run to investigate the application of insulin to reduce the vital state of hyperglycaemia." (PMID 34831179, 2021). "Black soybean seed coat extract also ameliorated hyperglycemia and insulin sensitivity in diabetic mice." (PMID 34199668, 2021). "For the patients of the present study, regular insulin was used to treat hyperglycemia during the surgical period." (PMID 34830501, 2021). "Many flavonoids are anti-diabetic by increasing secretion of insulin, improvement of hyperglycemia, reduce resistance to insulin and increase uptake of glucose by skeletal muscles in murine model." (PMID 33187049, 2020). "The management of hyperglycemia in the acute phase followed the recommendations of contemporary guidelines recommending the administration of insulin in patients with glucose concentrations > 140 mg/dL (7.8 mmol/L)." (PMID 32601437, 2020). "Glucose infusion rate required to maintain hyperglycemia (GIRHG) during the steady state was ~ 87% higher in TMBIM6−/− compared to WT mice suggesting increased glucose-stimulated insulin secretion and/or better insulin sensitivity in TMBIM6−/−." (PMID 32394396, 2020). "Although neurotrophic effects of insulin on sensory nerves have been shown, correcting hyperglycemia with insulin has little effect on dPNP in patients with T2DM." (PMID 32036431, 2020). "In T2D, especially during chronic and uncontrolled hyperglycemia, elevated glucose can have impairing effects on insulin-sensitive and insulin secreting tissues, termed glucotoxicity." (PMID 32183037, 2020). "Hyperglycemia resulting from the inflammatory response, insulin resistance, and pancreatic injury is described in severe COVID-19 infections." (PMID 33198177, 2020). "In T2D, the dysfunction of the insulin signaling mechanism results in the insensitivity to insulin in peripheral tissues, leading to hyperglycemia, hyperinsulinemia, and high levels of circulating lipids." (PMID 33147803, 2020). "Hyperglycemia has been linked to an increase in plasma renin activity with RAS activation, which is known to impair insulin signaling." (PMID 33120966, 2020). "Improved hyperglycemia and hypoinsulinemia are caused by the GLP-activation-induced increase in insulin secretion." (PMID 32825710, 2020). "Persistent hyperglycemia and a chronic inflammatory environment lead to oxidation-mediated stress and injury and also alter insulin sensitivity by triggering different key steps in the insulin-signaling pathway." (PMID 32878147, 2020). "Current management strategies provide insufficient guidance for glycemic control in individuals treated with GCs and GC-induced hyperglycemia is usually managed with insulin." (PMID 32381085, 2020). "Insulin does not pass the placenta, but glucose do, so the fetus becomes exposed to the maternal glycemic state, and in the event of hyperglycemia or fetal insulin resistance it secrets more fetal insulin." (PMID 32494038, 2020). "With intensive exercise, hyperglycaemia post exercise is aggravated by the inability to automatically increase insulin delivery into the portal circulation." (PMID 32533229, 2020). "The newly designed Ba salt/Insulin showed a visible significant effect on hyperglycemia at doses of 100 IU/Kg and % reduction in blood glucose is less than 50%." (PMID 32751231, 2020).
Hyperglycemia (continued). "The excess fatty acid in the pancreatic islets impairs beta-cell function, and the hyperglycemia further increases insulin secretion with consequent enhancement of hepatic lipogenesis." (PMID 33339276, 2020). "In type 2 diabetes (T2D), the inability of the cells to respond to low levels of insulin, defined as insulin resistance, leads to elevated glucose levels in the bloodstream, or hyperglycemia." (PMID 32194426, 2020). "Diverse studies have included estimations of insulin concentration in the body to avoid excessive insulin stacking; however, hypo- and hyperglycemia are still a hazard for AP systems, and novel approaches are still required." (PMID 32399164, 2020). "Concomitantly, clinicians should avoid hyperglycemia (>180 mg/dL) and implement insulin therapy carefully to prevent hypoglycemia." (PMID 32265626, 2020). "This situation affects the translocation of the glucose transporter type 4 (Glut-44) in insulin-sensitive tissues such muscle or fat, which leads to circulating glucose accumulation and consequently, to hyperglycemia." (PMID 32933003, 2020). "Formononetin reversed alloxan-induced hyperglycemia in mice through inhibition of β-cell apoptosis and promotion of cell regeneration, insulin secretion, and by increasing hepatic glycogen synthesis and hepatic glycolysis." (PMID 33379327, 2020). "Diabetes mellitus is a group of metabolic disorders characterized by hyperglycemia and insufficiency of secretion or action of endogenous insulin." (PMID 32595747, 2020). "On the other hand, when insulin boluses were based on carbohydrate estimates that were off by 20 g, more instances of hypo- and hyperglycemia occurred 2-3 hours after the meal." (PMID 33112249, 2020). "The initial respiratory acidosis increases through reduced metabolism and leads to hyperglycemia through reduced release of insulin and peripheral insulin resistance." (PMID 32630249, 2020). "Activation of the cholinergic parasympathetic innervation of the pancreatic islets, and inhibition of the sympathetic nervous system control insulin secretion in response to hyperglycemia." (PMID 33253166, 2020). "In conclusion, A. pilosa augmented serum insulin and adiponectin levels, prevented hyperglycemia, decreased serum FFAs, regulated hepatic expression of lipogenesis-related genes, and improved hepatic steatosis in ovariectomized rats." (PMID 32492866, 2020). "We report here that liraglutide ameliorates hyperglycemia in mice with type 1 diabetes by inducing insulin+glucagon+ cells and insulin-producing cells from the pancreatic ducts." (PMID 32477262, 2020). "Differences in glycemic control between the two groups were mainly observed in postprandial BG, suggesting that DU's mechanism of insulin secretion and glucagon suppression during hyperglycemia contributed to the lowering of postprandial BG." (PMID 31168938, 2020). "Because metformin and insulin have an inhibitory effect on appetite and hyperglycemia, we wanted to determine if T2DM subjects had different levels of NPY expression based on their treatment." (PMID 32814716, 2020). "Bolus insulin included rapid-acting insulin analogues and the delivered insulin to cover postprandial hyperglycemias." (PMID 32344939, 2020). "BCP upon oral administration appears to alleviate hyperglycemia and protect β-cells by increasing insulin release and preventing oxidative stress and inflammatory cytokines in pancreas and plasma of diabetic rats." (PMID 32998300, 2020). "Taken together, these results demonstrated that 2 months of fructose intake triggered metabolic derangements in spontaneously hypercholesterolemic ApoE-KO mice, which mimics human MetS characterized by dyslipidemia, high insulin levels and hyperglycemia." (PMID 33154969, 2020). "Compared with the wild-type mice, T1D mice exhibited severe hyperglycemia, low body weight, and few insulin levels with marked elevation of glycated hemoglobin (HbA1c)." (PMID 32646003, 2020).